INS (insulin)
Diseases named in the same sentence as INS in open-access papers (continued):
Sharing a sentence is not in itself a finding about the gene and the disease.
diabetes (continued). "In addition, researchers have indicated that higher rates of adherence (especially to diet-related recommendations) are associated with improved health outcomes among insulin-using patients with diabetes." (PMID 31094324, 2019). "Importantly, it has been described that defective insulin secretion by β-cells underlies all forms of diabetes mellitus." (PMID 31487953, 2019). "Good knowledge and favorable attitude towards insulin therapy, good knowledge regarding diabetes mellitus, being member of a diabetes association, older age (>30 years), getting insulin therapy for free and having glucometer at home were found to be the predictors of adherence to insulin therapy." (PMID 31692777, 2019). "Also, insulin is much less available compared to OHAs and access remains poor in many regions of the world, thereby placing needing patients at risk of diabetes-related complications and death." (PMID 30943969, 2019). "Dietary ingredients may play a key role in improving insulin sensitivity and reducing the risk of diabetes and its complications." (PMID 30862039, 2019). "The kinase AKT2 (PKB) is an important mediator of insulin signaling, for which loss-of-function knockout (KO) mutants lead to early onset diabetes mellitus, and dominant active mutations lead to early development of obesity and endothelial cell (EC) dysfunction." (PMID 31835296, 2019). "Diabetes mellitus (DM) is caused by a deficiency of either insulin production or insulin function." (PMID 31331038, 2019). "Therefore, this study was designed to assess the level of adherence to insulin therapy and associated factors among diabetes mellitus patients." (PMID 31692777, 2019). "In diabetes, increased oxidative stress at low heme oxygenase-1 levels and decreased insulin and insulin-like growth factor-1 signaling lead to loss of interstitial cells of Cajal, which results in abnormal gallbladder emptying and promotes gallstone formation." (PMID 31088424, 2019). "It was reported that apelin regulates insulin sensitivity, stimulates glucose utilization and enhances brown adipogenesis in different tissues associated with diabetes 12, 41, indicating the apelin–APJ system as a novel therapeutic target for pharmacological intervention in treating diabetes." (PMID 30868058, 2019). "Is decreased insulin signaling sensitivity such as in diabetes a cause of AD increase?" (PMID 30652125, 2019). "When used to treat mice, mitochondrial division inhibitor 1 (mdivi-1), a Drp1 inhibitor, rescues tubular mitochondrial network and membrane potential, decreases oxidative stress, and increases insulin-mediated glucose uptake in diabetes-susceptible cybrid cells." (PMID 31551926, 2019). "ABCA1 R230C/C230C genotypes might confers susceptibility to diabetes through insulin secretion and adipocyte function." (PMID 31010439, 2019). "Covariates associated with a higher risk of DR were duration of diabetes and insulin treatment." (PMID 31070699, 2019). "Exocrine pancreatic function has not been systematically explored, though it has been recently shown in one case of diabetes induced by nivolumab (anti-PD-1), with both a bi-hormonal deficiency (insulin and glucagon) and an exocrine pancreas insufficiency (asymptomatic reduction in fecal elastase)." (PMID 30400055, 2019). "Diabetes mellitus is a metabolic dysfunction of multiple etiologies, characterized by chronic hyperglycemia resulting from a deficiency in insulin secretion or the inability of insulin to exert its normal effects." (PMID 30916210, 2019). "Insulin-deficiency caused directly by proinsulin misfolding has been proved unequivocally in an autosomal-dominant form of diabetes known as Mutant INS-gene-induced Diabetes of Youth (MIDY), which occurs in patients bearing one mutant and one wild-type INS allele." (PMID 31184302, 2019). "Loss or attenuation of insulin signaling is a distinctive trait of diabetes." (PMID 31212580, 2019).
diabetes (continued). "Not only hyperglycemia, but high insulin level in diabetes can cause the ROS accumulation." (PMID 31455405, 2019). "We observed that increased concentrations of TNFα and IFNγ, associated with obesity and diabetes, might interfere with the anti-inflammatory effect of insulin, which in turn might promote inflammation." (PMID 31504048, 2019). "We hypothesized that the dMCV is related to the magnitude of serum hypertonicity caused by hyperglycemia in insulin-treated, clinically stable dogs with naturally-occurring diabetes." (PMID 31335875, 2019). "Metformin and exercise independently improve insulin sensitivity and decrease the risk of diabetes." (PMID 30548390, 2019). "Excessive lowering of blood glucose level during diabetes therapy, which frequently involves augmenting insulin effects directly or indirectly, might cause hypoglycemia and sometimes severe hypoglycemia." (PMID 31356602, 2019). "We previously proved that endothelial dysfunction was correlated with individual metabolic risk components, such as diabetes, dyslipidemia, hypertension or visceral obesity, but most strongly with clustering of the components under a condition with low insulin sensitivity." (PMID 30808962, 2019). "The loss of functional insulin-producing β-cells is a hallmark of diabetes." (PMID 31676778, 2019). "Indeed, among the participants from the ARIC study, the associations between insulin use and dementia risk attenuated after additional adjustment for diabetes duration." (PMID 30768625, 2019). "Although vascular complications of diabetes may also be responsible for the development of neurodegenerative diseases in advanced age, a direct contribution of impaired insulin signaling pathway has been implicated repeatedly." (PMID 31143098, 2019). "Whereas, loss of cellular energy due to glucose deficiency has been associated with morphological deterioration in some vital organs, studies of energy loss in diabetes animals suggest that effects of intensive insulin therapy on mitochondrial integrity would contribute to the clinical benefits." (PMID 28790167, 2019). "A recent study has shown that along with reduced insulin secretion, decreased glucagon suppression may contribute to the predisposition to diabetes conferred by TCF7L2." (PMID 30700996, 2019). "Its use in rheumatoid arthritis is associated with a reduced risk for developing diabetes in large observational studies, and its administration to healthy obese subjects without the metabolic syndrome increases the Matsuda index of insulin sensitivity." (PMID 31384309, 2019). "Diabetes mellitus is a metabolic and endocrine disorder characterized by hyperglycemia which leads to alterations in carbohydrate, lipid, and protein metabolism, associated with absolute or relative deficiencies in insulin secretion and/or insulin action." (PMID 32219004, 2019). "Therefore, zinc deficiency is associated with decreased insulin secretion and sensitivity, features that are characteristic of CF-related diabetes." (PMID 30642010, 2019). "Hypertension is also associated with conditions, such as obesity and diabetes mellitus, that further alter and damage microvasculature in presence of an inflammatory milieu, resulting in impaired endothelial insulin signaling and insulin-stimulated nitric oxide synthesis." (PMID 31023262, 2019). "However, a developing body of evidence has linked oxidative species with insulin signaling, and it has been postulated that diabetes mellitus is—to a considerable extent—caused by a failure of the organism to create enough oxidative redox potential." (PMID 30987358, 2019). "Type 2 diabetes mellitus (T2D), the most common subtype of diabetes is a disease characterized by hyperglycaemia and it arises from a varying combination of high resistance to action and relative deficiency of the hormone insulin." (PMID 30894049, 2019).
diabetes (continued). "Finally, further studies are necessary to elucidate the influence of aerobic exercise-modulated asprosin levels in adipose tissue, skeletal muscle, and blood using insulin-deficient animal models, in order to elucidate its role in the treatment of diabetes." (PMID 31083617, 2019). "Previous research has indicated that both ceramide and dihydroceramide may play a role in insulin sensitivity, and that increased levels of total dihydroceramide may be potential biomarker for diabetes susceptibility." (PMID 30828353, 2019). "Diabetes mellitus is a metabolic disorder which is characterized by hyperglycemia along with alterations in carbohydrate, lipid and protein metabolism associated with complete or relative deficiencies in insulin secretion and/or insulin action." (PMID 31142215, 2019). "While the decrease in these glucose transporters may be linked to a decrease in insulin secretion in diabetic mellitus state." (PMID 31513755, 2019). "Control of diet and exercise, and insulin sensitizers treatment to minimize insulin resistance and to mitigate the risk of relapse might be suitable for ketosis-onset diabetes after the initial hyperglycemia crisis." (PMID 31049079, 2019). "Two types of diabetes are recognized: Type 1 diabetes (T1D) results from the autoimmune destruction of the insulin‐producing pancreatic islet cells leading to loss of insulin production; type 2 diabetes (T2D) results from resistance to insulin and relative lack of insulin." (PMID 31249705, 2019). "Reduced or complete lack of insulin signaling is a hallmark of diabetes." (PMID 31212580, 2019). "Dysregulation of insulin signaling is linked to diabetes and cancer." (PMID 30931927, 2019). "Finally, we did not have direct assessments of endothelial and β-cell function and insulin levels, which would have helped our understanding of the underlying pathophysiology and temporal sequence between baPWV and diabetes." (PMID 31462258, 2019). "Diabetes mellitus is a chronic disease of the metabolism that leads to disturbances in the carbohydrate, protein, and lipid metabolisms due to a partial or absolute deficiency in insulin hormone secretion and/or the effect of insulin." (PMID 31372147, 2019). "However, as the present study was not designed to explore the pathogenic mechanisms underlying the association between SS and the development of diabetes, the insulin sensitivity in our study population remained unexplored." (PMID 31330868, 2019). "This inflammation could be causative for insulin signaling disorders in adolescents, clinically presenting as insulin resistance, glucose intolerance and type 2 diabetes mellitus." (PMID 31514755, 2019). "Insulin injection was associated with depressive symptoms in diabetes patients." (PMID 31726788, 2019). "STZ is an agent of choice to induce experimental diabetes mellitus due to its ability to induce specific necrosis of the pancreatic beta cells that results in degranulation and loss of capacity to secrete insulin, thereby leading to hyperglycemia and diabetic complications such as nephropathy." (PMID 31527864, 2019). "Some studies have reported that increased BMI is associated with increased insulin; therefore, BMI may be a confounding factor of diabetes and breast cancer." (PMID 30732565, 2019). "Some studies have shown emotional reactions may increase glycogenolysis, gluconeogenesis, and insulin resistance, decrease insulin secretion and subsequently increase the risk of diabetes in the patients." (PMID 31277616, 2019). "Thus, excessive ER stress or attenuation of the UPR in IPCs potentially causes destruction or functional inhibition of the cells, resulting in reduced insulin secretion and eventually causing diabetes." (PMID 31822470, 2019). "Omitting breakfast has been associated with obesity, hypertension, diabetes, and atrial fibrillation, and may also impair serum lipids and postprandial insulin sensitivity." (PMID 31443394, 2019).
diabetes (continued). "Furthermore, the rising prevalence of ketosis-prone diabetes among type 2 obese diabetics also bears a high risk for DKA recurrence after insulin discontinuation after the resolution of ketoacidosis." (PMID 31192058, 2019). "The American Diabetes Association guidelines (2015) lists insulin and metformin as preferred treatments, and states that glyburide may be used, but may have a higher rate of neonatal hypoglycemia and macrosomia." (PMID 31775682, 2019). "Cigarette smoking has been associated with low secretion of insulin along with high insulin resistance which may lead to diabetes." (PMID 31275662, 2019). "Insulin use at entry was associated with longer diabetes duration, worse glycaemic control, and a greater risk of chronic complications; it could influence health status and QoL." (PMID 31011577, 2019). "We assessed weight course in a real-life diabetes secondary care setting and analyzed its association with patient characteristics, lifestyle habits and initiation of insulin, glucagon like peptide-1 receptor agonists (GLP-1 RA) and sodium-glucose co-transporter-2 inhibitors (SGLT-2i)." (PMID 31216324, 2019). "Impairments in insulin regulation are associated with obesity, diabetes, cardiovascular disease, and hypertension, and abnormalities in neural insulin signaling pathways are associated with various neurodegenerative diseases and deficits in learning and memory." (PMID 31311133, 2019). "Androgen deprivation therapy for prostate cancer increases obesity, decreases insulin sensitivity, and may be associated with a greater incidence of diabetes." (PMID 30057912, 2018). "Indeed, the use of agents that suppress glucagon or its action can prevent hyperglycemia in insulin-deficient rodent models of diabetes." (PMID 30216981, 2018). "Before the current study, although the contribution of mitochondrial fusion and fission in IR in human and rodents is reported, it remains unclear whether changes in mtDYN directly affect insulin action with the diabetes-susceptible genotype background." (PMID 30363990, 2018). "Our results indicate that postmenopausal women with prior GDM are more insulin resistant than postmenopausal women controls of similar age, adiposity, and fitness levels and are as insulin resistant as women with T2DM further supporting conclusions that women with GDM are at risk for diabetes." (PMID 29951553, 2018). "The prevalence of GDM is generally proportional to the prevalence of underlying type 2 diabetes, and the risk for women with GDM to develop diabetes mellitus later in life depends on several factors, like follow-up time, insulin need during pregnancy, and ethnicity." (PMID 30477103, 2018). "An enhanced insulin management service provided substantial cost savings from improved glycemic control related to insulin dosing optimization and the associated reduction in utilization of expensive diabetes medications." (PMID 32685571, 2018). "Thus, an increased level of islet BCL11A expression was linked to established diabetes and impaired insulin secretion." (PMID 30242153, 2018). "For patients with T2D uncontrolled on oral antidiabetic drugs (OADs) or glucagon-like peptide 1 receptor agonists (GLP-1RAs), the American Diabetes Association (ADA) and the European Association for the Study of Diabetes (EASD) guidelines recommend the use of basal insulin as an alternative option." (PMID 29408938, 2018). "However, loss of CDK4 has been shown to result in insulin-deficient diabetes due to a severe decrease in β-cell growth." (PMID 29523786, 2018). "This may be because of the fact that when patients acquiesce to start insulin, they may already have diabetes for a long time with greater associated complications." (PMID 29736169, 2018).
diabetes (continued). "After adjusting for confounding factors by multivariate analysis, only older age, being male, being in Health Region 4, hypertensive comorbidity, presenting hyperglycemic crisis and insulin therapy remained significantly associated with IHD among patients with diabetes." (PMID 30053837, 2018). "Major questions remain as to its pathogenesis and whether it is a unique type of diabetes or a subset of more severe type 2 diabetes with greater loss of insulin action in target tissues." (PMID 30280274, 2018). "Since the incentives in the current study were successful at increasing exercise duration, our future goal is to target ways to increase exercise frequency, to increase the likelihood of increasing insulin sensitivity and to reduce the risk for diabetes in this population." (PMID 29856832, 2018). "The increased risk of diabetes may be related to our finding that a high dietary acidity load associates with impaired insulin sensitivity." (PMID 30292239, 2018). "A univariate logistic regression analysis revealed that a higher pre-pregnancy BMI (p = 0.0044), 2-h PG (p = 0.016), HbA1c (p < 0.0001), and the requirement of insulin therapy (p = 0.0031) were significant risk factors for the postpartum development of diabetes." (PMID 29310607, 2018). "mTORC2 inhibition is implicated in impaired glucose homeostasis, insulin insensitivity, and diabetes, though studies on worms with tissue-specific RNAi have suggested that it is loss of mTORC2 activity, specifically in the intestine that results in the dysregulation of glucose metabolism." (PMID 30096787, 2018). "Insulin replacement therapy is mostly used by patients with type 2 diabetes who become insulin deficient and have failed other therapeutic options (herein referred to as advanced diabetes)." (PMID 29682315, 2018). "Individuals discharged from the emergency department following hypoglycemic episodes who were taking oral diabetes medications are at a greater risk than individuals taking insulin alone of a return emergency department visit within 48 h for recurrent hypoglycemia." (PMID 29799604, 2018). "Among women with diabetes, insulin use (n = 53) was significantly associated with higher tumor protein expression of IGF1R (OR = 2.36; 95%CI:1.02–5.52; p = 0.04) and p-mTOR (OR = 2.35; 95%CI:1.13–4.88; p = 0.02), especially among women treated with insulin analogues." (PMID 29486734, 2018). "In diabetes, the progressive loss of the subbasal nerve plexus, combined with hyperglycaemic and oxidative damage to the lacrimal gland, likely drive a reduction in essential trophic factors, including insulin, that are secreted into the diabetic tear film." (PMID 29531349, 2018). "Therefore, cigarette smoking increases diabetes and insulin resistant risk factors, so resulting in high fasting blood glucose level." (PMID 30186808, 2018). "Furthermore, studies have suggested that iatrogenic hypoglycemia, caused by administration of insulin or of an insulin secretagogue, was associated with the death of patients with diabetes." (PMID 30105256, 2018). "Diabetes is a long-term metabolic disorder in which the blood glucose (BG) level varies and is caused by either insufficient insulin production in the body (Type 1 diabetes, T1D) or by the body’s inability to utilize its produced insulin (Type 2 diabetes, T2D)." (PMID 29986473, 2018). "Autocrine insulin signaling in β-cells plays a critical role in the maintenance of appropriate β-cell mass and insulin synthesis and secretion, defect insulin signaling is associated with declined β-cell mass and the onset of diabetes, which was well-documented in vitro and in vivo studies." (PMID 30409165, 2018). "Therefore, palmitic acid is known to cause insulin resistance by attenuating insulin signaling, while oleic acid has a protective effect against insulin resistance and type 2 diabetes mellitus." (PMID 30405056, 2018). "For example, insulin has been suggested to cause sodium retention in diabetes." (PMID 30343339, 2018).